SKAP1 (src kinase associated phosphoprotein 1)
Diseases named in the same sentence as SKAP1 in open-access papers (continued):
Sharing a sentence is not in itself a finding about the gene and the disease.
prostate carcinoma (2 papers, 2012 to 2021). A carcinoma that arises from epithelial cells of the prostate gland. "In The Cancer Genome Atlas (TCGA) prostate cancer data, reduced SKAP1 expression is associated with a younger age of diagnosis, and expression is reduced in prostate adenocarcinoma relative to normal prostate." (PMID 34059701, 2021). "A genetic variant within SKAP1 has previously been found to be associated with prostate cancer specific mortality." (PMID 34059701, 2021). "Our results indicate that evaluation of an additional locus sentinel, rs559612720 in SKAP1, would more fully capture prostate cancer risk of this locus than rs138213197 in HOXB13 alone." (PMID 34059701, 2021). "Moreover, a man who had inherited both HOXB13 G84E and the SKAP1 sentinel could have considerably greater risk of early onset, aggressive prostate cancer than might be appreciated by knowledge of G84E carriage alone." (PMID 34059701, 2021). "SKAP1 (rs6504145) in Han Chinese populations was detected to affect prostate cancer specific mortality in advanced prostate cancer populations, and variation in FBXO32 (rs7830622) and FLT1 (rs9508016) appeared to affect all-cause mortality in advanced prostate cancer." (PMID 22956944, 2012). "Study patients who did not carry the HOXB13 variant but carried the SKAP1 variant had 3.6-fold elevated risk for prostate cancer, not baseline risk as might otherwise be interpreted by a negative clinical HOXB13 test." (PMID 34059701, 2021).
Autoimmunity (1 paper, 2023). The occurrence of an immune reaction against the organism's own cells or tissues. "Ongoing research on SKAP1 and its binding partners will likely provide important insights into the regulation of immune function and have implications for the development of new treatments for disease states such as cancer and autoimmunity." (PMID 37325633, 2023). "This may involve assessing the impact of SKAP1 on specific immune cell subsets or its place in various affected disease states such as autoimmunity, transplant rejection, and cancer." (PMID 37325633, 2023).
colorectal tumors (1 paper, 2015). "However, three transcripts (SKAP1, ARHGAP24, and NT5E) were up-regulated in PMP but generally down-regulated in colorectal tumors." (PMID 25929336, 2015).
osteoarthritis (1 paper, 2022). A noninflammatory degenerative joint disease occurring chiefly in older persons, characterized by degeneration of the articular cartilage, hypertrophy of bone at the margins and changes in the synovial membrane. "In SKAP1 deficient mice, it was found that IL17 cytokines decreased and T-cell infiltration decreased, which alleviated collagen-induced osteoarthritis." (PMID 35754830, 2022).
cancer (9 papers, 2012 to 2024). A tumor composed of atypical neoplastic, often pleomorphic cells that invade other tissues. "Because NETs mediate the pro‐tumor activity of neutrophils, we investigated a potential functional link between cancer cell expression of SKAP1 and NET formation." (PMID 39269257, 2024). "Instead, we found a potent in vivo tumor‐promoting effect of SKAP1 in mice and consequently revealed a novel SKAP1‐induced cellular interaction between cancer cells and neutrophils, which largely accounted for its pro‐tumor activity." (PMID 39269257, 2024). "Due to its restricted expression to immune cells, the SKAP1 pathway appears to have evolved as an additional immune cell specific pathway by which immune cell receptors regulate T-cell division in response to foreign pathogens and cancer neoantigens." (PMID 31320682, 2019). "We found that some tertiary lymphoid structure-related genes such as LAT, RBP5, SKAP1, and CCR6 were positively correlated with MHCsig in pan-cancer." (PMID 38714579, 2024). "Several of the other genes are relevant to cancer—in addition to ERBB2, SKAP1 is an adaptor for Src, DEPTOR regulates the mTOR pathway and NRIP1 is an estrogen-receptor coregulator." (PMID 23260012, 2012). "Quantitative analysis revealed that SKAP1 protein expression was significantly higher in cancer tissues than in noncancerous tissues." (PMID 39269257, 2024). "The biological function of SKAP1 related to these cancer types is not yet well elucidated." (PMID 37383672, 2023).
tumor (7 papers, 2015 to 2025). "The blockade of CXCL8 or NFATc1 largely attenuated neutrophil infiltration, NET formation, and tumor promotion induced by SKAP1." (PMID 39269257, 2024). "As a result, SKAP1 overexpression led to markedly larger tumors at the time of sacrifice and an almost 2.5‐fold increase in tumor weight (0.81 ± 0.16 g versus 0.33 ± 0.07 g, P < 0.01)." (PMID 39269257, 2024). "This study revealed that enhanced NET formation is an important neutrophil‐related mechanism contributing to the tumor‐promoting effect of SKAP1." (PMID 39269257, 2024). "We then investigated which specific function of neutrophils is responsible for the tumor‐promoting effect of SKAP1." (PMID 39269257, 2024). "Enhanced formation of neutrophil extracellular traps (NETs) is found to be a key downstream event that contributed to the pro‐tumor role of SKAP1." (PMID 39269257, 2024). "In the NK cell‐treated groups, SKAP1 knockdown significantly prolonged the survival of tumor‐bearing mice." (PMID 39269257, 2024). "SKAP1 expression has been observed to be correlated with cytotoxic T cell PD-1 expression, suggesting a role in tumor tolerance." (PMID 34059701, 2021). "The enhanced formation of NETs in SKAP1‐overexpressing tumors was further confirmed by immunofluorescence staining for citrullinated histone H3 (Cit‐H3), another specific marker of NETs, in tumor‐infiltrating neutrophils." (PMID 39269257, 2024). "Additionally, NET degradation by DNase I substantially reduced the SKAP1 overexpression‐induced survival disadvantage in HCT116 tumor‐bearing mice." (PMID 39269257, 2024). "In addition, NK cell therapy offered a greater survival benefit in mice with SKAP1‐knockdown SW620 tumors than in control tumor‐bearing mice." (PMID 39269257, 2024). "CXCL8, besides being a neutrophil chemotactic factor, also acts on endothelial cells and exerts angiogenic activity in the tumor microenvironment, suggesting that SKAP1 may promote tumor progression through the CXCL8‐dependent regulation of angiogenesis." (PMID 39269257, 2024). "Unexpectedly, we observed a potent in vivo tumor‐promoting effect of SKAP1 in nude mice." (PMID 39269257, 2024). "Compared to normal tissues, significantly higher expression for SKAP1, LAT and lower expression for CD1D, CD79B, CETP, PTGDS was found in tumor tissues in the TCGA-BRCA cohort." (PMID 37598257, 2023). "SKAP1 (also known as SKAP55) is an adapter protein of the T-cell receptor at the interface of CD8 cytotoxic T lymphocytes and tumor cells, functioning in adhesion and anti-tumor immune response." (PMID 34059701, 2021). "Although our study emphasizes the crucial role of the CXCL8‐NET axis, we cannot rule out other mechanisms involved in SKAP1‐induced tumor promotion." (PMID 39269257, 2024). "SKAP1 overexpression led to a more than 2.4‐fold increase in HT‐29 tumor weight in IgG‐treated mice (0.65 ± 0.05 g versus 0.26 ± 0.08 g, P < 0.001) 28 days after tumor implantation, but failed to significantly increase tumor weights in anti‐Ly6G antibody‐treated mice (P > 0.05)." (PMID 39269257, 2024). "To test this hypothesis, we analyzed various tumor‐infiltrating immune cells using flow cytometry and found that there were significantly more CD11b+ Ly6G+ neutrophils, rather than other detected immune cells, in SKAP1‐overexpressing HCT116 tumors." (PMID 39269257, 2024). "NPG mice bearing SKAP1‐overexpressing HCT116 tumors were injected with NK‐92MI cells together with or without DNase I. NK cell treatment slowed the growth of SKAP1‐overexpressing HCT116 tumors, as revealed by tumor volume and weight measurements." (PMID 39269257, 2024).
infection (1 paper, 2025). The state of being infected such as from the introduction of a foreign agent such as serum, vaccine, antigenic substance or organism. "Contrary to SKAP1 gene the methylation changes associated with STIM2 gene appear to take part in infection progression because methylation levels at CpG sites associated with this gene differed between infection stages." (PMID 40537863, 2025).
SKAP1 also shares sentences with these, for which no sentence is quoted: lymphoma (2 papers); melanoma (2); Arthritis (1); asthma (1); bladder cancer (1); breast tumours (1); Colon (1); epithelial ovarian tumors (1); hematologic cancers (1); leukemia (1); malignant fibrous histiocytoma (1); prostate adenocarcinoma (1); viral infection (1).